NF1 (neurofibromin 1)
Diseases named in the same sentence as NF1 in open-access papers (continued):
Sharing a sentence is not in itself a finding about the gene and the disease.
tumor (continued). "Although OPGs are histologically low grade, their heterogeneous clinical behavior driven by tumor proximity to vital structures, younger age at presentation and NF1 association makes a “one-size-fits-all” treatment strategy controversial." (PMID 37519788, 2023). "Phase I/II trials on selumetinib have demonstrated its stability or reduction of tumor size in pediatric patients with NF1-associated and sporadic form of pLGGs, with similar results observed in a study of children with progressive/recurrent PA." (PMID 37397394, 2023). "As an important RasGAP, NF1 functions as a tumor suppressor in multiple tumors, and loss of NF1 is common and associated with tumor growth as well as resistance to targeted therapy in CRC." (PMID 37355626, 2023). "The use of a genetic panel in patients with NF1 and other types of neoplasia is a powerful tool to better understand the genotype and phenotype relationships involved in this rare tumor association, and it can identify new mutations." (PMID 36629684, 2023). "Loss of NF1 results in the infiltration of tumor-associated macrophages into the tumor microenvironment, causing mesenchymal transition and radioresistance to chemotherapy." (PMID 37175412, 2023). "This guideline aims to assimilate available information on NF1 associated tumours (based on evidence and/or expert opinion) to assist healthcare professionals in undertaking tumour surveillance of NF1 individuals." (PMID 36684394, 2023). "Additional MAPK-activating mutations seemed to be less frequent for BRAFMUT tumours with 1/12 (8.3%) case harbouring an NF1 mutation." (PMID 38066305, 2023). "Daginakatte & Gutmann (2007) examined tumor specimens from human NF1-associated PAs and found microglia in all specimens." (PMID 38318325, 2023). "NF1 is caused by mutations in the tumor-suppressive gene, NF1, which result in aberrant activation of the RAS signaling pathway." (PMID 38203448, 2023). "NF1 loss-of-function mutations have been associated with increased tumor immunogenicity, infiltration of immune cells, and potential responsiveness to immunotherapies." (PMID 37504268, 2023). "In the present case, the tumor was a 75-mm-diameter MPNST arising in the pelvis in association with NF1, and the prognosis was considered poor." (PMID 37672135, 2023). "NF1 inactivation leads to the activation of the mTOR pathway and promotes tumour cell growth; therefore, mTOR inhibitors can be used in potential therapies for NF1-deficient patients." (PMID 38024139, 2023). "Functionally, NF1 is a tumor suppressor that encodes a protein that activates the Ras guanosine-triphosphate (GTP)ase, which in turn downregulates Ras by inducing the hydrolysis of GTP bound to Ras (Ras-GTP), its activated form." (PMID 37627552, 2023). "It is caused by inherited or de novo mutations in the gene encoding neurofibromin 1 (Nf1), a GTPase-activating protein, which is highly expressed in the neuronal cells and acts a tumour suppressor by negatively regulating Ras pathways." (PMID 36899941, 2023). "It is of note that the tumor mutational burden is the highest in NF1-mutated tumors followed by NRAS mutants." (PMID 36980598, 2023). "We retrospectively compared the change in FASI size to the change in tumor size among children treated with selumetinib on stratum 3 (children with NF1-associated LGG) of PBTC-029." (PMID 37046770, 2023). "This guideline addresses surveillance for tumour types associated with NF1,16,20 offers guidance on the imaging modalities for surveillance, on the age to start and the interval between assessments." (PMID 36684394, 2023).
tumor (continued). "An international multicentre NF1 registry including longitudinal natural history data regarding NF1-associated tumours is essential, but challenging and a task for institutions dedicated to rare diseases." (PMID 36684394, 2023). "A bias in the NF1-associated size of facial tumor extensions in favor of more advanced and extensive manifestations in a reference center for the treatment of NF1 patients is very likely." (PMID 37534339, 2023). "Of note, very few studies have examined sex-dependent differences in NF1-mutated tumor initiation and growth." (PMID 36826025, 2023). "For patient 1a, we found an oncogenic splice region variant in the neurofibromatosis type 1 (NF1) gene at very low allele frequency in the tumor tissue." (PMID 37796616, 2023). "NF1 is a tumor suppressor gene that encodes the neurofibromin protein and negatively regulates Ras signaling." (PMID 35702826, 2023). "Two cases exhibited somatic KMT2D mutations, of which one tumor also carried a somatic NF1 mutation." (PMID 36656469, 2023). "In this study, we also found a pathogenic variant in NF1 (c.7152_7153insT) in the tumor and in the germline of a patient with a MPNST." (PMID 36805510, 2023). "NF1, a tumor suppressor gene, and RAS‐GTPase are causally linked to the acquisition of the mesenchymal subtype in GBM, promoting cell invasion, proliferation, and tumorigenesis." (PMID 36776000, 2023). "NF1 acts as a tumor suppressor gene that encodes neurofibromin, a large protein that controls neoplastic transformation through several molecular mechanisms." (PMID 37627552, 2023). "Increased PI3K activity can be caused by the loss of tumor suppressors such as PTEN phosphatase or neurofibromin 1 (NF1)." (PMID 37174072, 2023). "ANNUBP is a newly defined NF1-associated tumor that manifests as nuclear atypia, hypercellularity, and increased mitotic activity; thus, its malignant potential is uncertain." (PMID 36831419, 2023). "The tumor inclination condition known as NF1 is associated with a variety of sensory system tumors as well as low‐grade gliomas (LGG) in the pediatric population." (PMID 37675821, 2023). "Additional studies are needed to better understand the impact of sex on NF1-mutated tumor biology in human and in animal models." (PMID 36826025, 2023). "Accordingly, we observe that NDI1 thwarts tumorigenicity of NF1-related tumor cells, directly demonstrating a causal connection between a decrement in the activity of respiratory complex I and neoplastic growth." (PMID 35393510, 2022). "While immunohistochemistry for STAG2 did not provide evidence for a complete loss of expression in tumor cells, 7/11 (63.6%) oligosarcomas showed a tumor cell specific loss of NF1 expression." (PMID 34967922, 2022). "Neurofibromatosis 1 (NF1) is an autosomal dominant disorder caused by inherited or de novo germline mutations within the NF1 tumor suppressor gene." (PMID 36358751, 2022). "This suggests that Nf1 mutations associated with tumor formation cause RGC neurons to be hyperexcitable." (PMID 35589737, 2022). "The NF1 gene is a tumor suppressor gene, and its encoded neurofibroma protein is a Ras GTP enzyme activator protein (RAS gap)." (PMID 36211008, 2022). "For example, in tumour P12-NBL, RAS-MAPK activation in the primary tumour occurred through loss of NF1, whilst it occurred in the metastatic lesion due to BRAF-mutation." (PMID 36182817, 2022). "Loss of tumor suppressors NF1 and PTEN were reported, and TERT, a gene encoding a telomere maintenance protein enabling replicative immortality, was amplified." (PMID 35229492, 2022).
tumor (continued). "Gain of chromosome 7, loss of chromosome 10 and homozygous deletion of the CDKN2A locus were confirmed in all analyzed tumor parts, as was the TERTp duplication and an NF1 frameshift mutation." (PMID 36114166, 2022). "These tumor–stroma interactions are nicely illustrated in the setting of the neurofibromatosis-1 (NF1) genetic cancer predisposition syndrome." (PMID 35589737, 2022). "Finding a mutation in H3-3A in a tumour carrying a germline NF1 variant suggests that perhaps some mutations in NF1 do need another alteration that confers additional selective advantages to the tumour cells." (PMID 36760809, 2022). "External reports stated an additional NF1 stopgain mutation for the tumor of patient 18 that also presented with NF1 loss via immunohistochemistry." (PMID 34967922, 2022). "The NF1 gene is located on 17q11.2 and encodes a tumour suppressor that works as a GTPase-activating protein to deactivate the RAS/MAPK signalling pathway, finally causing the occurrence of tumours." (PMID 36505786, 2022). "Taken together, these results position RAS-mediated neuron midkine production downstream of HCN channel activity, and demonstrate that increased baseline excitability of tumor-associated Nf1-mutant neurons is RAS-independent." (PMID 35589737, 2022). "One should necessarily not mix up that constitutional MMR pathogenic gene variants such as in CMMRD are associated with a distinct tumour syndrome that only focally resembles NF1." (PMID 34997843, 2022). "The objective of the present study was therefore to investigate the association between contrast enhancement, tumor volume, and visual function in NF1 + OPG and spOPG patients to refine indications for GBCA administration." (PMID 34994964, 2022). "While complete loss of NF1 expression is necessary for tumor formation, heterozygosity for a germline mutation can cause significant cognitive and behavioral impairments in children with NF1." (PMID 35188187, 2022). "NF1 germline mutations cause a disorder called neurofibromatosis 1, characterized by changes in skin pigmentation and the development of different tumor types." (PMID 35626065, 2022). "Genomic DNA sequencing allowed us to identify additional genetic alterations including mutations in the PTPN11 (encoding SHP-2) and BRAP genes that were associated with enhanced NF1-related tumor malignancy." (PMID 35625983, 2022). "Recently, dual SDHB/NF1 loss has been reported as a successful mechanism to force tumour formation in a SDHB knockout mouse model." (PMID 36760809, 2022). "The presence of NF1 somatic mutations is one of the main genetic findings occurring in sporadic PPGLs (accounts for 20-25% of all cases), being mostly tumours with adrenal location and only 4% extra-adrenal." (PMID 36760809, 2022). "Collectively, these findings reveal that NF1 mutations act at the level of neurons to modify tumor predisposition by increasing neuronal excitability and activity-regulated paracrine factor production." (PMID 35589737, 2022). "To test the feasibility of ATR inhibition in the treatment of high-grade neoplasms, we evaluated NF1- and ATRX-deficient cancer cells." (PMID 35740680, 2022). "Studies have shown an increased radiosensitivity in NF-1 patients, which can lead to increased side effects from irradiation and a higher risk of secondary tumor induction." (PMID 35832560, 2022). "In April 2020, selumetinib, a MEK inhibitor, was the first drug approved by the US Food and Drug Administration (FDA) for the treatment of an NF1-associated tumor." (PMID 35291225, 2022). "The most frequently mutated gene, among this selection, is NF1, mutated in 2% of the cases, with truncating mutations in 57 tumor samples and splice-site mutations in 21 samples (with three patients having more than one NF1 mutation)." (PMID 36358725, 2022). "Some chromosomal abnormalities, notably deletion of chromosome 17q and neurofibromin (in NF-1 patients), have been regarded as the underlying etiology of this tumor." (PMID 36230704, 2022).
tumor (continued). "For example, an increased level of tumor-associated macrophages was detectable in the case of NF1 deficiency." (PMID 34687436, 2022). "Mutations in the NF1 gene are also present in the tumor DNA of patients primarily resistant to BRAF inhibitors and patients with early or acquired resistance to these drugs." (PMID 35565444, 2022). "NF1-related GIST is a tumor with low malignancy and risk, with resistance to imatinib, which generally do not require treatment." (PMID 36620543, 2022). "We show that central and peripheral nervous system neurons from mice with tumor-causing Nf1 gene mutations exhibit hyperexcitability and increased secretion of activity-dependent tumor-promoting paracrine factors." (PMID 35589737, 2022). "In contrast to the low expression levels of CXCR4 and its ligands, CXCL12, in the embryonic SC lineage as the origin of NF1-deficient tumors, high levels in tumor cells from MPNST mouse models were measured by Western blotting." (PMID 36139671, 2022). "Monitoring children with both NF1 + OPGs and spOPGs aims at detecting visual loss and potential tumor growth as early as possible in order to start treatment in time." (PMID 34994964, 2022). "But besides the first/germline and a second/somatic hit of the wildtype NF1 allele, other factors modify tumour development." (PMID 34997843, 2022). "The somatic pathogenic NF1 mutation in Case 2 tumor was associated with a classic second-hit (loss of the wild-type allele), similar to other conventional somatic loss of function NF1 mutations." (PMID 36440216, 2022). "In the current study, we found that as a tumor suppressor gene, NF1 had the most frequent mutation in the RTK-RAS pathway in patients with LM." (PMID 33777740, 2021). "Neurofibromatosis type 1 (NF-1) is a common genetic disorder caused by loss-of-function mutations in the NF1 tumor suppressor gene, which encodes neurofibromin, a GTPase activating protein negatively regulating the activity of the proto-oncogene Ras." (PMID 33708774, 2021). "In this study, we demonstrated that NF1 caused by whole gene deletions of the NF1 gene leads to a more severe phenotype with higher tumor burden and higher averaged annual growth rates when compared with NF1 without large deletions of the NF1 gene." (PMID 33951044, 2021). "NF1-associated GIST is difficult to diagnose because of unusual location of tumor in small intestine." (PMID 34274754, 2021). "Evidence to support this diagnosis of MPNST was available for 4 of 11 cases, with two tumours arising in patients with germline NF1 alterations (cases 224 and 798) and two others associated with deep‐sited nerves (cases 811 and 960)." (PMID 33949149, 2021). "40% (16/40) of the cohort had at least one tumor and 10% (4/40) had two or more, which demonstrates the significant tumor predisposition effect of the entire NF1-spectrum." (PMID 34325699, 2021). "They affect the biochemical alterations in the development of NF1-linked tumors especially in malignant transformation process or tumor grades." (PMID 34566848, 2021). "Its heterozygosity initiates PNF formation and increases the tumor number in a Nf1-deficient mouse model by stimulating SCP self-renewal and promotion of tumorigenesis." (PMID 34566848, 2021). "Unfortunately, the embryonic lethality of Nf1−/− mutation makes it impossible to use mice carrying such mutations as tumor models." (PMID 34359780, 2021). "Increased or extended EGFR-dependent progenitor cells were found in tumor tissues of NF1-deficient mice and upregulation of EGFR stimulates the activation of the downstream signaling, the MAPK cascade." (PMID 34948100, 2021).
tumor (continued). "NF1 patients have about four-fold higher risk of neoplasms through dysregulation of the RAS/MAPK pathway." (PMID 33530415, 2021). "Conversely, immunonegative results in some VHL and NF1 mutated tumours compromise specificity of SDHB immunohistochemistry." (PMID 34834591, 2021). "NF1-GEMMs have been the cornerstone for the development and testing of new therapies for NF1-associated neoplasia." (PMID 33669386, 2021). "Previous studies on tumor resistance due to NF1 loss mainly focused on the activation of Ras/RAF kinases, such as the Raf-MEK-ERK pathway." (PMID 34795217, 2021). "Nonetheless, genetically engineered mouse models have significantly improved our understanding of NF1-associated tumor biology and have unique advantages for testing new prognostic and therapeutic tools." (PMID 33669386, 2021). "Most commonly, the pathogenesis of these neoplasms is driven by inactivating mutations of the NF1 gene." (PMID 34530870, 2021). "Strikingly, heterozygosity for Nf1 in mast cells elicits tumor formation in mice with biallelic loss of Nf1 in Schwann cells." (PMID 33708774, 2021). "This tumor progression is related with loss of heterozygosity of NF1 gene function in the Schwann lineage cells." (PMID 34948100, 2021). "Since overexpression and hyperactivation of EGFR is often found in NF1-associated MPNST tumor tissues and cells, we examined the expression level of pEGFR by IHC." (PMID 34948100, 2021). "NF1 patients, who carry a deleterious mutation in one allele of the gene encoding the NF1 tumor suppressor, develop benign plexiform neurofibromas when a “second hit” inactivates the remaining functional NF1 gene in a cell within the Schwann cell lineage." (PMID 33707600, 2021). "Radiation therapy to the tumor in this population is generally avoided due to the risk of secondary malignancy and the risk of moyamoya syndrome in patients with NF1." (PMID 34885143, 2021). "These tumours arise as a result of gain-of-function-mutations in RET or mutations in genes such as NF1, TMEM127, MAX, MET, MERTK and FGFR1 and HRAS (both somatic)." (PMID 34834591, 2021). "Most likely, the existence of a NF1-MAPK-FOSL1 axis goes beyond GBM pathogenesis since FOSL1 appears to be upregulated in concomitance with NF1 mutations in multiple tumor types." (PMID 34399888, 2021). "For example, NF1 deficiency resulted in increased infiltration of tumor-associated macrophages and microglia." (PMID 34276757, 2021). "Mutation in NF1 gene, which encodes neurofibromin, causes loss of its function and results in Ras activation, promoting the tumor formation." (PMID 34274754, 2021). "NF1 whole gene deletions cause a more severe phenotype of NF1 with higher tumor burden and higher growth-rates compared to NF1 patients without large deletions of the NF1 gene." (PMID 33951044, 2021). "Similar studies with larger cohorts found individual variables associated with survival, such as tumor size, margin status, NF1 diagnostic status, and tumor grade." (PMID 34646065, 2021). "NF1, encoding neurofibromin, is a good example to illustrate the role of GAPs in the tumor immune microenvironment." (PMID 34663417, 2021). "•The treatment often mandates surgical resection of the tumor and the prognosis of NF1-associated GIST patients is good." (PMID 34274754, 2021). "NF1 mutations lead to altered levels of cytokines, mast cells, macrophages, microglia, T and B cells, and they both directly affect immune cells and indirectly affect interactions between different NF1-mutated cells important for the tumour microenvironment." (PMID 35008787, 2021).